DUSP29 (dual specificity phosphatase 29)
Description:
Dual specificity phosphatase able to dephosphorylate phosphotyrosine, phosphoserine and phosphothreonine residues within the same substrate, with a preference for phosphotyrosine as a substrate. Involved in the modulation of intracellular signaling cascades. In skeletal muscle regulates systemic glucose homeostasis by activating, AMPK, an energy sensor protein kinase (By similarity). Affects MAP kinase signaling though modulation of the MAPK1/2 cascade in skeletal muscle promoting muscle cell differentiation, development and atrophy (By similarity).
Synonyms: DUPD1; DUSP27; FMDSP
Tractability: No criterion of Open Targets' tractability assessment is met for any kind of drug.
Gene: Protein-coding gene on chromosome 10 (75,037,472 to 75,073,655, reverse strand). Ensembl gene ENSG00000188716.
Subcellular location: Cytoplasm; Nucleus
Gene Ontology:
Molecular function: protein binding; protein homodimerization activity; protein serine/threonine phosphatase activity; protein tyrosine phosphatase activity; protein tyrosine/serine/threonine phosphatase activity; MAP kinase phosphatase activity; phosphatase activity
Biological process: protein dephosphorylation; muscle cell differentiation; negative regulation of ERK1 and ERK2 cascade; negative regulation of MAPK cascade; glucose homeostasis
Cellular component: cytoplasm; protein-containing complex; nucleus
Genetic constraint (gnomAD): Loss-of-function variants: 14 observed, 15.18 expected, observed/expected ratio (o/e) 0.92, 90% interval 0.61 to 1.44. The upper end of that interval is the gene's LOEUF score, 1.44, which puts it in group 5 of 6, group 1 being the genes least tolerant of losing a copy. Missense variants: 308 observed, 317.76 expected, observed/expected ratio (o/e) 0.97, 90% interval 0.88 to 1.07. Synonymous variants: 134 observed, 137.14 expected, observed/expected ratio (o/e) 0.98, 90% interval 0.85 to 1.13.
Homologues: Orthologues: chimpanzee DUSP29 (98% identical), macaque DUSP29 (95% identical), dog DUSP29 (86% identical), rabbit DUSP29 (85% identical), pig DUSP29 (85% identical), guinea pig DUSP29 (82% identical), mouse Dusp29 (82% identical), rat Dusp29 (81% identical), tropical clawed frog dusp29 (61% identical), zebrafish si:ch211-121a2.2 (42% identical), zebrafish si:dkeyp-27c8.1 (32% identical), zebrafish si:dkey-194e6.2 (31% identical), and 1 more. Paralogues in human: DUSP13A (42% identical), DUSP13B (42% identical), DUSP26 (41% identical), DUSP3 (34% identical), STYXL2 (33% identical), SSH1 (29% identical), SSH2 (28% identical), SSH3 (28% identical), DUSP8 (27% identical), DUSP7 (26% identical), DUSP1 (25% identical), DUSP18 (25% identical), and 19 more.
Diseases named in the same sentence as DUSP29 in open-access papers:
DUSP29 is named in the same sentence as 1 disease in open-access papers, as found by Europe PMC text mining. Sharing a sentence is not in itself a finding about the gene and the disease.
DUSP29 shares sentences with these, for which no sentence is quoted: cancer (1 paper).